RNU1-67P (RNA, U1 small nuclear 67, pseudogene)
Gene: Small nuclear RNA gene on chromosome X (119,423,742 to 119,423,905, forward strand). Ensembl gene ENSG00000207175.
Homologues: Orthologues: chimpanzee U1 (98% identical). Paralogues in human: RNU1-1 (95% identical), RNU1-2 (95% identical), RNU1-27P (95% identical), RNU1-28P (95% identical), RNU1-3 (95% identical), RNU1-4 (95% identical), RNVU1-18 (95% identical), RNVU1-29 (95% identical), U1 (95% identical), RNVU1-28 (95% identical), RNVU1-7 (95% identical), RNVU1-31 (94% identical), and 133 more.